TSPY10 (testis specific protein Y-linked 10)
Description:
May be involved in sperm differentiation and proliferation.
Tractability: PROTAC: ubiquitination databases record sites on it.
Gene: Protein-coding gene on chromosome Y (9,527,880 to 9,530,682, forward strand). Ensembl gene ENSG00000236424.
Subcellular location: Cytoplasm; Nucleus
Subcellular location (Human Protein Atlas): Cytosol
Gene Ontology:
Molecular function: protein binding
Biological process: nucleosome assembly
Cellular component: chromatin; cytoplasm; nucleus
Homologues: Orthologues: macaque TSPY2 (71% identical), zebrafish tspy (28% identical), Drosophila melanogaster Set (23% identical), Caenorhabditis elegans spr-2 (19% identical), Drosophila melanogaster Nap1 (15% identical), Caenorhabditis elegans nap-1 (14% identical), Drosophila melanogaster CG3708 (12% identical), Drosophila melanogaster mil (12% identical), zebrafish nap1l4a (12% identical). Paralogues in human: TSPY3 (100% identical), TSPY4 (100% identical), TSPY9 (99% identical), TSPY1 (99% identical), TSPY2 (99% identical), TSPY8 (99% identical), TSPYL1 (34% identical), TSPYL4 (32% identical), TSPYL5 (31% identical), TSPYL2 (31% identical), TSPYL6 (29% identical), SET (26% identical), and 6 more.